IL6 (interleukin 6)
Diseases named in the same sentence as IL6 in open-access papers (continued):
Sharing a sentence is not in itself a finding about the gene and the disease.
Sepsis (continued). "The mutant displayed sustained release of IL-6 compared to TNF-α during co-culturing with A549 lung cell lines, attenuation in mice sepsis model, and significantly reduced ability to adhere to and invade A549 lung cells and form biofilms on abiotic surfaces." (PMID 34950110, 2021). "During sepsis, LPS-induced HIF-1α activation promotes the production of inflammatory cytokines (including TNF-α, IL-1β, and IL-6) and proapoptotic mediators, resulting in inflammation and apoptosis." (PMID 33567713, 2021). "In a neonatal murine E. coli sepsis model, IL-27Rα-/- mice showed lower levels of TNF-α, IL-1β and IL-6, and improved survival rates." (PMID 34079555, 2021). "Studies of experimental sepsis have indicated that HBO2 treatment exerts its antimicrobial effect by enhancement of IL‐10, which lowers IL‐6 and thereby reduces the overall mortality in HBO2‐treated animals." (PMID 33719215, 2021). "In the sepsis group, testicular MDA, TNF-α, and IL-6 levels increased and SOD activity decreased compared with the sham group." (PMID 35317115, 2021). "We showed better reductions in the AST, ALT, serum creatine, and cytokine levels (IL-6, IL-10, TNF-α, IFN-γ, MIP-2, and MCP-1) in both the early and late stages of sepsis." (PMID 34759282, 2021). "Various databases were searched to collect published studies on the diagnosis of sepsis in adult patients using neutrophil CD64, PCT, and IL-6 levels." (PMID 33902476, 2021). "Procalcitonin compared to IL-2, IL-6, IL-8 and TNF-α also has the highest sensitivity and specificity for differentiating patients with SRIS from those with sepsis." (PMID 34577795, 2021). "Thirty hours after induction of sepsis, testicular samples were collected to measure SOD activity and MDA, IL-6, and TNF-α levels." (PMID 35317115, 2021). "In the animal sepsis model, the expression levels of inflammatory factors, such as TNF-α, IL-1, and IL-6, are significantly elevated in brain tissues, accompanied by the increased cerebral water content and brain permeability to blood dyes." (PMID 34592907, 2021). "In another CLP-induced polymicrobial sepsis model, EA downregulated the level of TNF-α, IL-6, nitrite, and high-mobility group box 1 (HMGB-1) in serum, and reduced nuclear fraction NF-κB p65 activity in the spleen." (PMID 35095910, 2021). "Cardiac dysfunction and inflammation were observed in sepsis rat, which were characterized by the decrease of LVSP and + dp/dtmax, the increase of LVEDP, − dp/dtmax, cTnI, CK-MB, TNF-α, IL-1β, IL-6." (PMID 34376255, 2021). "By 4 h p.i., 7 additional cytokines were significantly reduced, including TNF, IL-6, and CXCL1 (KC) which have major roles in sepsis pathogenesis." (PMID 34873199, 2021). "Cytokine secretion mediates brain dysfunction, and the increases of IL-1β, IL-6, and TNF-α are involved in cognitive impairment after sepsis." (PMID 35111693, 2021). "The laboratory indexes of the clinical diagnosis of sepsis include C-reactive protein (CRP), procalcitonin (PCT), and IL-6." (PMID 33505221, 2021). "As models for sepsis studies, hu-BLT mice had high levels of human IL-6 in sera after cecal ligation and puncture (CLP)-surgery and are more susceptible to CLP-induced sepsis than C57BL/6 mice." (PMID 34620229, 2021). "It has been reported that serum cytokines such as IL-1β, IL-6, IL-8, IL-10, IL-12, IL-17A, IL-18, interferon gamma (IFN-γ), and TNF-α are elevated in sepsis, but some of these cytokines are also elevated in FMF patients." (PMID 34654467, 2021). "The levels of HBP, IL-6, PCT, N%, and D-dimer were significantly higher in the severe sepsis group than in the sepsis group." (PMID 34778149, 2021). "We then identified inflammation in the mice with sepsis myocardial injury, and the levels of TNF-α, IL-6, IL-8, and IL-10 were evaluated using ELISA." (PMID 33819192, 2021).
Sepsis (continued). "During the development of sepsis, several inflammatory cytokines, including IL-1, TNF-α, and IL-6, are released and thus initiate downstream pathways that lead to cell death and organ disorder." (PMID 32892306, 2021). "In our study, 20 studies were included, showing that the neutrophil CD64 test has a high sensitivity and specificity in adult sepsis patients, and was superior to the traditional biomarkers PCT and IL-6." (PMID 33902476, 2021). "Another study suggested that both CRP and IL-6 more accurately identified severe sepsis and septic shock than sTREM-1, although sTREM-1 did outperform PCT in diagnosing severe sepsis." (PMID 33803628, 2021). "The gene expression of inflammatory mediators including IL-6 and TNF-α was also elevated after sepsis." (PMID 33859538, 2021). "NF-κB participates in the development of sepsis by enhancing the transcription of proinflammatory cytokines, such as TNF-α, IL-6, and IL-1β." (PMID 34616305, 2021). "For example, lncRNA PVT1 induces an increase in TNF-α, IL-6, and IL-1β release, and promotes inflammation by regulating TNF-α and JNK/NF-κB signaling pathways in sepsis." (PMID 33710444, 2021). "The expression level of MALAT1 was significantly increased in sepsis in vitro, and MALAT1 knockout also reduced serum levels of cTn-I, TNF-α, IL-1β, IL-6, IL-10, IL-17, IFN-γ, C5, and C5a." (PMID 34514170, 2021). "The MSCs on the SF nanofibers significantly reduced plasma IL-6 and TNF-α levels, which were increased by polymicrobial sepsis induction within 24 h." (PMID 33946773, 2021). "Among these biomarkers, IL-6 showed the best performance, with AUCs of 0.82 and 0.85 in the NSTI and sepsis cohorts, respectively." (PMID 34263738, 2021). "We found that LPS-induced sepsis elicited increased the serum level and mRNA expression of TNF-α and IL-6 in cardiac tissues." (PMID 35005242, 2021). "Mice with sepsis showed an obvious intestinal barrier dysfunction with decreasing specific somatostatin receptor subtype (SSTRs), and increasing TNF-α, IL-6, and IL-10 in the ileum." (PMID 33376482, 2020). "Levels of inflammatory markers like tumor necrosis factor-alpha (TNF-α), interleukin-1-beta (IL-1β) and, interleukin-6 (IL-6) as well as VEGF, a specific sepsis marker in plasma, were quantified." (PMID 33371296, 2020). "The results obtained showed that the rats in the untreated sepsis group showed significantly elevated levels of pro-inflammatory cytokines (IL-1α, IL-2, TNF-α, IL-6, IFN-γ, IL-1β) in plasma." (PMID 32076015, 2020). "Peritonitis-induced sepsis resulted in gradually increased plasma levels of TNF-α and IL-6, providing evidence of a progressive systemic inflammatory response." (PMID 32117276, 2020). "Currently, anti-inflammatory treatment such as IL-1 receptor blockade, anti-IL-6, and anti-TNF are considered to be promising approaches in the early stage after the onset of sepsis, but it is too costly." (PMID 32153410, 2020). "In conclusion, our findings indicate that the serum IL-6 level is positively correlated with the serum levels of PAI-1 in patients with CRS, including those with sepsis or ARDS." (PMID 32826331, 2020). "Interestingly, not any combination of MRproADM with CRP, PCT, and/or IL6 could increase the diagnostic accuracy for sepsis (data not shown)." (PMID 32831638, 2020). "The expression levels of TNF-α, IL-6, and IL-1β were significantly increased inthe CLP group compared with the sham group, indicating that sepsis promotedinflammation." (PMID 32578720, 2020). "In this study, we observed the severe inflammatory damage with increase of TNF-α, IL-6, and IL-10 in the ileum from the CLP-induced sepsis model, which was consistent with the previous study." (PMID 33376482, 2020). "The researchers also observed that the levels of IL-1β, IL-6, IL-10, MCP-1, and TNF-α were significantly increased in septic shock as compared with severe sepsis." (PMID 32153410, 2020).
Sepsis (continued). "It is well studied that both IL-6 and TNF-α are the primary mediators of local inflammation and sepsis." (PMID 32079307, 2020). "At the early stage of sepsis, activated macrophages release a large amount of pro-inflammatory cytokines such as TNF-α, IL-1β, IL-6 to resolve invading pathogens and injured tissues, playing pivotal role in host defense." (PMID 32415087, 2020). "The production of plasma CRP by hepatocytes is controlled in part by IL-6 and consistent with a study of preterm infants with suspected sepsis, our findings are consistent with those showing a positive relationship between CRP and IL-6 plasma levels." (PMID 32479514, 2020). "Furthermore, accurate quantification of CRP and IL-6 in sepsis and COVID-19 may be crucial for predicting outcomes, thus potentially enabling early therapeutic interventions and therapy control, e.g., in response to mechanical ventilation or Tocilizumab treatment." (PMID 32912236, 2020). "In the present study, our findings indicated that rats with sepsis showed higher levels of d‐lactic acid, FD‐40, MDA, DAO, IL‐10 and IL‐6, compared with the sham group, but the SOD activity was decreased in sepsis rats." (PMID 32383354, 2020). "The activity of MPO, the levels of pro-inflammatory cytokines, including TNF-α and IL-6, in the intestine, the activity of DAO and the content of MDA in the serum in the sham, sepsis and sesamin (50 μM) + sepsis groups were examined." (PMID 32893702, 2020). "We found that the PKM2 tetramer agonist TEPP-46 protects mice from endotoxemia and sepsis induced by LPS or CLP by reducing the release of TNF-α and IL-6." (PMID 33542713, 2020). "During sepsis, HIF-1α, stimulated by LPS, activates the generation of inflammatory cytokines (including TNF-α, IL-1β and IL-6) and proapoptotic proteins, leading to inflammation and apoptosis." (PMID 32353952, 2020). "In another study, a cut-off level for IL-6 was 21.5 pg/mL, with 75% sensitivity, 82% specificity, 92% PPV, and 52% NPV for neonates with culture confirmed sepsis." (PMID 33233806, 2020). "The median concentrations of IL-6, PCT, and CRP were statistically significantly higher in each study subgroup (N-SIRS, SIRS, and sepsis subgroups) compared to the control group." (PMID 32655314, 2020). "In conclusion, our results found that mice with sepsis showed an obvious intestinal barrier dysfunction with an increase of TNF-α, IL-6, and IL-10 in the ileum." (PMID 33376482, 2020). "It was suggested that the serum levels of IL-6, IL-8, and TNF-α were significantly higher whereas those of IL-10, IL-13, and TGF-β were significantly lower in the sepsis group than those in the sham group." (PMID 31830649, 2020). "In both groups (isoflurane and Propofol), exposure to cecal ligation and puncture (CLP)/sepsis-inflammation led to increased fluid requirements, lower MAP at 8 h, development of a base deficit, and increased interleukins (IL-6, IL-1β, and TNF-α) at 8 h." (PMID 33392215, 2020). "When comparing the Sepsis-G group to the sham and Sepsis-C groups at 72 h, only the Sepsis-C group demonstrated significant increases in TNF-α and IL-6 expressions." (PMID 32295272, 2020). "On the other hand, in a CLP-induced sepsis model in HSP70.1/3 knockout mice, NF-κB binding/activation, TNFα and IL-6 in lungs and mortality were increased." (PMID 31612270, 2020). "Intraperitoneal injection of asiaticoside, a triterpenoid saponin, in CLP-induced mice, reduced the serum levels of IL-6 and TNF-α, the expression of COX-2 and iNOS in lung tissue, and the severity of lung injury due to sepsis." (PMID 33193799, 2020). "Expression of the pro‐inflammatory cytokines TNF‐α, IL‐6, and chemokines like MIP‐2 and KC mRNA in lung tissues was increased in CLP‐induced sepsis and was significantly reduced with miRNA 130b‐3p mimic treatment by 63, 56, 75, and 47.5%, respectively." (PMID 31724825, 2020).
Sepsis (continued). "The reduced TNF-α and IL-6 levels were correlated with the increased IL-10 and TGF-β levels in sera of CLP-induced sepsis mice treated with rSj-Cys compared with the CLP group without treatment." (PMID 32423469, 2020). "The detection of inflammatory mediators of each group showed that LPS significantly increased the levels of TNF-α, IL-6, IL-1β, and MCP-1, and decreased the level of IL-10, consistent with those results discovered in mice with sepsis-induced kidney injury." (PMID 33197894, 2020). "In the CLP model of sepsis, blocking TRPA1 increases disease severity as well as the levels cytokines IL-1β and IL-6 in mice." (PMID 33193423, 2020). "In the ileal tissues of healthy mice, sepsis EVs (S-EVs) downregulated messages of the pro-inflammatory cytokines including TNF-α, IL-1β, IL-6, IL-17A, and IL-22." (PMID 33182773, 2020). "We then examined the serum levels of inflammatory cytokine TNF-α, IL-6, IL-1β, and IL-10, and the clinical markers of acute systemic inflammation MCP-1 and CRP by ELISA in LPS-induced sepsis model." (PMID 32457606, 2020). "The level of IL-6 usually increases earlier than that of PCT and CRP, making it a potential biomarker for early detection among sepsis patients." (PMID 33198109, 2020). "P2Y12 receptor-deficient mice also showed diminished production of inflammatory mediators (i.e., IL-6, TNF-α, IL-10, and MIP-1) and reduced sepsis-induced lung injury." (PMID 33519492, 2020). "Existing biomarkers for sepsis, such as c-reactive protein (CRP), procalcitonin (PCT), and IL-6, have limited specificity and sensitivity." (PMID 32214905, 2020). "We found that the levels of IL-6, TNF-α, IL-1β, and MCP-1 were significantly increased at 24 h after sepsis." (PMID 32273831, 2020). "GTS-21, a synthetic selective stimulant of α7nAchR, has been shown to reduce myocardial injury via modulating inflammation (decreases in IL-6, IL-1β, TNF-α and activation of NF-κB P65) and apoptosis in LPS-induced sepsis in mice." (PMID 32194424, 2020). "Pro-inflammatory cytokines IL-6 and TNF-α play essential roles in the onset and progression of sepsis, and their over-expression was seen as an early signal suppressing myocardial contraction and the major cause of progressive systolic dysfunction." (PMID 32423469, 2020). "The results of the present study showed a significant increase (<0.001) in IL-6 and CRP concentrations among culture proven sepsis and clinical sepsis cases compared to controls." (PMID 33233806, 2020). "In MRSA-induced sepsis mouse model, XBJ decreased the secretion of IL-6, TNF-α, MCP-1, MIP-2, and IL-10 in sera and alleviated lung, liver, and kidney damage." (PMID 32153410, 2020). "In this work, three inflammatory cytokines with different action, IL-8, IL-12/23 p40, and IL-6, and CRP were taken to indicate inflammatory processes or sepsis." (PMID 32842482, 2020). "TNF-α and IL-1 enhance inflammatory cascade by activating macrophages to release certain proinflammatory cytokines such as IL-6 and IL-8, ROS/RNS, and lipid mediators which are essential to sepsis-induced organ failure." (PMID 33158114, 2020). "Based on the ROC curve analysis, it was shown that of all the biomarkers tested, only two—IL-6 and procalcitonin—had potential usefulness in the diagnosis of SIRS/sepsis in children with fever." (PMID 32655314, 2020). "During sepsis, there is a marked increase in typical pro-inflammatory cytokines, such as TNF-α and IL-1, which subsequently induce the production of IL-6." (PMID 32722013, 2020). "The deleterious role of IL-6 has been demonstrated in different models of AKI, including ischemic AKI, nephrotoxin-induced AKI and sepsis-induced AKI." (PMID 32880774, 2020). "Sepsis rats generated by cecal ligation puncture had significantly reduced TNF-α and IL-6 levels after XBJ treatment." (PMID 32082396, 2020).
Sepsis (continued). "After knockdown ofmiR-451a, the increased levels of IL-1β, IL-6 and TNF-α were reduced significantly(all P < 0.01), indicating that the inhibition of miR-451a in sepsis led to suppressedinflammation." (PMID 33211058, 2020). "In particular, expression values of miR‐1‐3p were related to plasma concentrations of the inflammatory markers IL‐6, NGAL and vasopressor requirements in sepsis." (PMID 32916773, 2020). "Sepsis is a lethal condition, accompanied by acute inflammatory responses, with the release of multiple inflammatory factors such as TNF-α and IL-6." (PMID 32188465, 2020). "By 24 h after the operation, the Sepsis-G group exhibited higher tumor necrosis factor (TNF)-α, IL-6, and IL-10 gene expressions than the sham group and higher TNF-α and IL-6 expressions than those of the Sepsis-C group." (PMID 32295272, 2020). "We observed that IL-6 and TNF-α were induced in sepsis mouse models and MEG3 was able to restrain their protein levels." (PMID 32410866, 2020). "Discovering inhibitors of the induction of IL-6 in inflammatory conditions is an important medical issue; this is particularly true for AKI in sepsis systemic inflammatory response that remains a devastating complication due to the lack of efficient treatment." (PMID 32089648, 2020). "So, many sepsis markers, like C-reactive protein (CRP), procalcitonin (PCT), and interleukin-6 (IL-6), are emerging to improve its diagnosis." (PMID 33061986, 2020). "Following sepsis induction by CLP, the pro-inflammatory cytokines, IL-1β, IL-6, tumor necrosis factor (TNF)-α, and monocyte chemoattractant protein (MCP)-1, showed a marked increase." (PMID 32943679, 2020). "Stimulation with LPS leads to increased secretion of pro-inflammatory cytokines, including IL-6, TNF-α, and IL-1β in the bloodstream, which are resulted from exacerbation of inflammation in patients with sepsis." (PMID 32079307, 2020). "In a clinical study, the levels of IL-1β, IL-6, TNF-α, etc., except for IL-10, were inhibited in the late phase of sepsis, while, in an animal study, the immune suppression status was attenuated with administration of the adenovirus Ade-HIF-1α." (PMID 32089644, 2020). "The results suggested that CLP-induced sepsis mice stimulated the secretion of pro-inflammatory cytokines (TNF-α and IL-6), but inhibited the regulatory immune pathway (lower levels of IL-10 and TGF-β)." (PMID 32423469, 2020). "The following contents of this review will highlight the immunomodulators that improve T cell immune responses during sepsis, such as IL-7, PD1/ PDL1-specific antibodies, IFN γ, G-CSF /GM-CSF, IL-15, IL-1ra, and anti-IL-6 antibody." (PMID 32197507, 2020). "The highest IL-6 median serum concentration was reported in the SIRS group (32.6 pg/ml (13.8-94.0 pg/ml)), followed by the sepsis and N-SIRS groups (26.4 pg/ml (11.5-71.4 pg/ml) and 18.1 pg/ml (8.5-29.2 pg/ml), respectively)." (PMID 32655314, 2020). "Collectively, these data suggest that the PKM2 tetramer agonist TEPP-46 protects mice from endotoxemia and sepsis induced by LPS or CLP by reducing the release of TNF-α and IL-6." (PMID 33542713, 2020). "Other biomarkers that can indicate the immune state in sepsis patients include apoptosis markers (Bim, Bid and Bac), caspases, leukocyte markers (HLA-DR, PD-1, FOXP3, CD127) and cytokines (IL-2, IL-6, IL-12, IL-17, IL-22, IL-33, TNF-α, IFN-γ, IL-10 and TGF-β)." (PMID 33336293, 2020). "This study defines the optimal cut-off values for IL-6 and CRP in the first five days of serial measurements using large number of culture-proven sepsis cases." (PMID 33233806, 2020). "Sepsis patients with elevated IL-6 are at a higher risk of developing cardiac dysfunction which may be due to direct negative inotropic effect of IL-6 mediated via altered production of myocardial nitric oxide, altered calcium homeostasis and impaired β-adrenergic signaling." (PMID 33584641, 2020).